ALB (albumin)
Diseases named in the same sentence as ALB in open-access papers (continued):
Sharing a sentence is not in itself a finding about the gene and the disease.
infection (continued). "However, when a patient develops an infection, the liver synthesises stress response proteins such as CRP, which in turn reduces the amount of ALB synthesis, leading to an increase in CRP/ALB ratio levels." (PMID 41019129, 2025). "For the multiple stepwise regression analysis, cortisol level was set as the dependent variable, and the independent variables included age, gender, BMI, HbA1c, blood glucose at admission, ACTH at admission, bicarbonate, albumin, blood lipid levels, ALT, blood creatinine, and presence of infection." (PMID 39959617, 2025). "The infection was complicated with low serum-ascites albumin gradient (SAAG), high protein, culture-negative, neutrophil-predominant ascites, devoid of visceral perforation, or an alternative etiology for ascites." (PMID 40642698, 2025). "Additionally, the levels of TC, Cr, GLU, and HbA1c were notably elevated, and the levels of ALB and HDL were significantly reduced in the infection group (average p < 0.01)." (PMID 40125519, 2025). "The ROS generated during the infection triggers the release of antioxidants molecules, including SOD, GPx, catalase, albumin, ceruloplasmin, ferritin, ascorbic acid, α-tocopherol, β-carotene, reduced glutathione, uric acid, and bilirubin, all of which are included in the measurement of TAS." (PMID 39852665, 2025). "In particular, the group with non-severe infection had greater values for body weight, age of onset, Hb, ALB, GLB, HDL, Mg,fibrinogen, TT, IgG, IgA, C3, and duration of steroid use." (PMID 41291834, 2025). "Despite the critical nutritional status, the albumin concentration of patient 9 was still in the lower normal range as long as there was no infection." (PMID 40732135, 2025). "constructed a prediction model with relatively better predictive performance (AUC=0.867) based on age, albumin to globulin ratio (AGR), NLR, CRP, ESR, mean platelet volume (MPV), comorbid infections, pleural effusion, primary disease, duration of fever, and wheezing." (PMID 40171163, 2025). "The results indicated a significant reduction in the infection rate: from 62% for rabbits with non-coated implants to just 27% for those with albumin-coated implants." (PMID 40565919, 2025). "During the period without infection, the albumin concentration was at the lower limit of the normal range." (PMID 40732135, 2025). "Despite broad-spectrum antimicrobial therapy and a comprehensive infectious workup, the patient exhibited rising PCT levels (peak 4.5 ng/mL) and declining albumin levels, with no microbiological evidence of infection." (PMID 41492631, 2025). "CRP levels were numerically but not statistically higher, and serum albumin levels were numerically lower in patients who had a PEG site infection." (PMID 38463403, 2024). "The serum protein profiles remained constant for 72 h after infection, as the globulin/albumin ratios did not change at any time point (p > 0.05)." (PMID 38540062, 2024). "Nutritional risk (OR=2.888) and HbA1c showed positive associations (P<0.001), while duration of HIV infection, albumin, and CD4+ T cell counts demonstrated negative associations with infection risk (P<0.05)." (PMID 39866736, 2024). "Albumin content in brain homogenates was equivalent between TNF KO and WT mice throughout the course of craniotomy infection, indicating that differences in BBB permeability were not responsible for the transient reductions in leukocyte recruitment observed in TNF-deficient animals." (PMID 39044282, 2024). "Together, these data indicate that neither H. haemolyticus nor rHpl exposures elevated lung immunopathology compared with NTHi infection alone, and instead, some responses including lung MPO and barrier permeability (as measured by albumin levels) were reduced." (PMID 38380941, 2024).
infection (continued). "Secondary outcomes involved the evaluation of mean daily gastric residual volume, mechanical ventilation period, infection rates within the ICU, length of hospitalization, mortality rates, nutritional status and inflammatory markers, specifically serum albumin and interleukin-6 levels." (PMID 38906990, 2024). "Serum albumin is depressed during inflammation, and thus, it is intuitive that patients presenting with exacerbations of COPD or infection may have lower serum albumin." (PMID 38744793, 2024). "The ICU patients had severe COVID-19 infections, so their biochemical parameters were higher than those of non-ICU patients except for Ca and albumin, which correlated negatively with the severity of the infection." (PMID 38618472, 2024). "While non-C. albicans were conventionally thought to be “non-damaging” in epithelial cell-culture infection models, recently, it was discovered that adding albumin to the cell-culture medium increased C. glabrata-induced epithelial damage." (PMID 39412273, 2024). "Significantly, this study underscores the diagnostic value of examining albumin and globulin ratios, with the albumin percentage and the albumin/globulin ratio (ALB/GLOB) showing moderate negative correlations with serological evidence of infection." (PMID 39204236, 2024). "Decreased plasma CRTAC1 could result from decreased production as occurs with ALB and TTR, increased turnover as occurs during severe infection with GSN serving as a scavenger for filamentous actin being released from cells, or a combination of mechanisms." (PMID 37667413, 2023). "Serum albumin, being a negative acute-phase reactant protein, is correlated with the severity of infection." (PMID 37817258, 2023). "The condition of lobsters was generally not affected by the parasite, as the hepatopancreatic index and the concentration of cholesterol, protein, and albumin did not vary with grade of infection." (PMID 37773971, 2023). "Collectively, these data suggest that GSK3β activity is not required to drive the downregulation of megalin in our experimental setting and that under IV infection conditions, downregulation of albumin uptake is independent of GSK3β activation." (PMID 37727782, 2023). "Other indicators, including low-density lipoproteins, urea, uric acid, creatine, calcium, serum globulin, albumin and total protein, were not significantly changed by infection." (PMID 38152255, 2023). "Serum albumin is a negative acute phase marker that decreases during acute inflammation and infection." (PMID 37762893, 2023). "Levels of ALB and AFR were significantly lower in infection group (P < 0.05)." (PMID 38111666, 2023). "However, when used separately, both serum albumin and LDH levels can be affected by many medical conditions, aside from infection." (PMID 36614820, 2022). "Clarkson reported that turkeys exhibited decreased albumin and elevated globulin concentrations at 12-day post-infection as compared to the non-challenged controls." (PMID 35601402, 2022). "Basic studies have explained that the main mechanism of decreased ALB production and elevated GLO levels during chronic inflammation or infection may be the increase in the fractional catabolic rate and the accumulation of inflammatory cytokines in serum GLO." (PMID 35907808, 2022). "In vivo, a 4%-concentration of non-oxidized albumin infusion reversed multimerization with a decrease in care-related infections." (PMID 36297613, 2022). "Because albumin levels drop during injuries and infection, albumin is referred to as a negative active-phase protein." (PMID 36589182, 2022). "A declining trend in log CRP was seen by excluding the 2 subjects strongly suspected of having an infection, although no increase in albumin levels was demonstrated." (PMID 35949598, 2022).
infection (continued). "When infection and inflammation occur, the level of serum CRP rises rapidly within a few hours, and reaches the peak in 24–48 h, however, serum ALB might be declined a few days after the initiation of pancreatic inflammation." (PMID 36704518, 2022). "Compared with the negative control group, the levels of ALB and TP in sera of chickens in the infection control and vector control groups (L. lactis/pTX8048, E. faecalis/pTX8048) decreased significantly (p < 0.01)." (PMID 35837390, 2022). "The allocation of CKD patients based on serum albumin levels is helpful in prediction of infection-related death, but not available in this study due to limited number of subjects." (PMID 34579200, 2021). "Indeed, infections with different inocula (multiplicity of infection (MOI) of 1, 5, 10, 50 and 100) revealed that damage increased even in albumin-free conditions." (PMID 34710198, 2021). "Preincubation of the fungus 1 h prior to infection with albumin (followed by its removal) also did not neutralize the fungal damage capacity to kidney cells." (PMID 34154403, 2021). "Owing to their high abundance in circulation and interstitial fluids, however, human serum albumin (HSA) and other plasma proteins were found to be the major target for HOCl and as such, represent the main scavenger of HOCl at sites of infection and inflammation [17,18,]." (PMID 33940547, 2021). "To investigate the consequence of the observed ER-stress response on infection, we pre-induced ER-stress in A-431 cells, by pre-incubating them with tunicamycin, before C. glabrata infection in the presence or absence of albumin." (PMID 34710198, 2021). "Mean serum albumin levels were significantly lower in DENV 3 and 4 infections." (PMID 34136322, 2021). "Post infection integrity of the alveolar-capillary barrier in myeloid KLF4 KO and KLF4 WT mice was assessed by determining the concentration of albumin in the bronchoalveolare lavage fluid (BALF) over that in plasma 24 hours after transnasal inoculation with PBS or 5x105 CFU NCTC 7978 pneumococci." (PMID 34589087, 2021). "Since preincubation of host or fungal cells failed to reduce damage, this suggests that albumin acts by neutralizing candidalysin during its release by invading C. albicans hyphae during infection." (PMID 34154403, 2021). "The lack of a difference in alanine aminotransferase (ALT), and the reduced values for blood albumin (ALB) and blood urea nitrogen (BUN), when uninfected and infected deer mice were compared suggests that infection did not cause liver and kidney impairment." (PMID 34127676, 2021). "The importance of glucose for C. glabrata pathogenicity was underscored by infections in the absence of glucose, where C. glabrata proliferation rates were significantly lower and no tissue damage in the presence of albumin was induced." (PMID 34710198, 2021). "Levels of plasma albumin did not vary significantly according to time, diet or infection (repeated measures ANOVA, factorial ANOVA)." (PMID 34732186, 2021). "Compared to those with a single infection, CHIKV/DENV co-infected participants had higher mean systolic blood pressure (p = 0.03) haemoglobin (p = 0.01), haematocrit (p = 0.03), bilirubin (p = 0.002) and albumin (p = <0.001)." (PMID 33930028, 2021). "To shed light on the mechanisms by which C. glabrata induces epithelial damage, we analyzed the transcriptional responses of the epithelial cells during infection in the presence and absence of albumin (a PCA plot of all analyzed samples is shown in S2C Fig)." (PMID 34710198, 2021). "Overall, these results indicate how low albumin (reflective of malnourishment, as well as infection owing to its negative acute phase protein property), high CRP, and old age correlate with inpatient mortality in an additive manner." (PMID 34207560, 2021).
infection (continued). "Further analysis showed that 1 h of preincubation of kidney cells alone with albumin (followed by its removal) prior to infection did not affect the ability of C. albicans to damage kidney cells." (PMID 34154403, 2021). "However pre-albumin, RBP and CHI, are all greatly influenced by renal function, infection and trauma as well." (PMID 31936748, 2020). "Two had IgG serum trough levels <5 g/l, two of 40 were deficient in vitamin B12, four of 41 in vitamin D and one of 43 in albumin (all not due to infection)." (PMID 32849570, 2020). "It was also observed that both NV1505 and PG1505 were able to significantly reduce S. pneumoniae counts in the lungs, prevent its dissemination into the blood and reducing BAL albumin and LDH values in ELP-treated infant mice after the primary infection with RSV." (PMID 32660087, 2020). "The albumin level of patients with severe infection was significantly lower than patients without severe infection." (PMID 33330582, 2020). "Pre-albumin, which is not a part of the albumin to globulin ratio, decreased significantly with increasing infection density." (PMID 32995005, 2020). "Slightly decreased levels of ALB were observed in S. japonicum group, which was reversed by T. gondii prior infection, although showed no significance after analysis." (PMID 32295161, 2020). "However, albumin levels do not solely reflect endogenous albumin production, but may also be low due to infection/inflammation, or an increased albumin loss or high in the case of albumin substitution, for instance, in patients that frequently require large volume paracenteses." (PMID 31717529, 2019). "Albumin, on the other hand, is a negative acute-phase reactant decreasing in the acute period of infection and/or inflammation." (PMID 31803551, 2019). "Prealbumin and albumin are negative acute phase proteins: they decrease in infection, inflammation, and trauma." (PMID 31420744, 2019). "Albumin is a negative acute phase protein whose level tends to decrease in inflammation or infection." (PMID 29554918, 2018). "Nevertheless, the interpretation of globulin alone is usually not of clinical importance because the decrease in actual albumin/globulin ratio is needed to confirm an acute phase reaction in infection or inflammation in dogs." (PMID 30551591, 2018). "The results of this profile showed that infection with both DENV-3 strains induced some of the same parameters on day 3 p.i., including lower albumin, alkaline phosphatase, and total bilirubin; however, albumin was lower in C0360/94-infected mice (1.8 versus 1.5 g/dL, p = 0.046)." (PMID 29559699, 2018). "Serum albumin, hsCRP, WBC, and ferritin individually might reflect a different pathophysiological pathway on cardiovascular, infection-related, or other mortalities." (PMID 29494637, 2018). "Additionally, the positive correlation in the second blood sample between the albumin/globulin ratio and the CD4/CD8 ratio indicated that both defence systems (humoral and cell-mediated) were engaged because of an infection (predominantly viral)." (PMID 29596432, 2018). "Aged mice exhibited higher levels of serum albumin in BALF at 24 hpi than young mice, indicating that the epithelial barrier of aged mice was destroyed more severely than that of young mice after infection." (PMID 30018181, 2018). "Fourth, since the nutritional status affects infection and mortality, we do not have the data of body mass index and serum albumin level." (PMID 30227675, 2018). "Regarding the pooled MD of albumin between the infection group and the non-infection group was MD = −2.28 (95 % CI −3.97–0.58), which was statistically significant (z = 2.63, P = 0.008)." (PMID 28093079, 2017). "Total protein and albumin are serum proteins synthesized by the liver that are not only affected by nutritional status, but by inflammation and infection." (PMID 28421202, 2017).
infection (continued). "CSF controls were characterized by normal CSF cytology, physiological protein concentrations, normal albumin and immunoglobulin quotients and absence of oligoclonal IgG bands, thus excluding inflammation, infection and impairment of the blood–brain-barrier." (PMID 28806983, 2017). "The pooled MD of albumin between the infection group and the non-infection group was MD = −2.28 (95 % CI −3.97–0.58), which was statistically significant (z = 2.63, P = 0.008)." (PMID 28093079, 2017). "Low serum albumin has not been confirmed as a factor driving HS/DS or the result of long term infection." (PMID 28464844, 2017). "At a higher infection dose, 6 × 106 PFU, the renal injury was more severe, accompanied by higher levels of proteinuria and urinary GAGs excretion, and lower levels of serum albumin." (PMID 27747195, 2016). "To test this hypothesis we administered Evans Blue (EB), a dye with high affinity to serum albumin, to IFNAR-/- B6 mice at the peak of infection with LASV or MORV." (PMID 27191716, 2016). "During the course of infection and human IFNα treatment, we observed no significant decrease in the human hepatocyte content of the chimeric livers based on serum human albumin levels." (PMID 26765841, 2016). "The lack of association between serum ferritin and infection-related mortality in the multivariate analysis including CRP, albumin and several comorbidities indicated that serum ferritin acts not only as iron storage but as acute phase reactant." (PMID 26599216, 2015). "In the group of patients with HRS and active bacterial infection, 8 of 17 patients (47 %) showed response treatment with terlipressin and albumin, while 18 of 41 patients (43.9 %) without active infection showed response (p > 0.05)." (PMID 26722626, 2015). "However, at 23 hr post-infection, greater amounts of FITC-albumin were detected in the blood of PA99Sbla-infected mice compared to PA99null-infected mice, indicating that ExoS contributed to disruption of the pulmonary-vascular barrier during infection." (PMID 26090668, 2015). "So-called negative acute phase proteins like transferrin, α-2-HS-glycoprotein, fibronectin and pre-albumin were consistently reduced in malnourished children, even without infections." (PMID 25153531, 2014). "Of the respondents, 46.1 % of surgeons use chlorhexidine baths at home preoperatively for insertions, 42.5 % obtain preoperative laboratories (such as albumin, prealbumin, TWBC, TLC, serum transferrin) to stratify for infection, and 30.8 % obtain MRSA swabs to guide preoperative antibiotic choice." (PMID 24744235, 2014). "Albumin is considered to be a negative acute phase protein because serum concentrations decrease in inflammation and/or infection." (PMID 25430894, 2014). "Four other studies of cirrhotic patients with infection compared the use of antibiotics with and without albumin." (PMID 24222902, 2013). "More studies are needed to evaluate if albumin reduces adverse outcomes among cirrhotic patients without paracentesis or infections." (PMID 24222902, 2013). "However trends were observed in liver chemistry values including decreased albumin (ALB), and increased alanine aminotransferase (ALT) and blood urea nitrogen (BUN) suggesting those animals that died from infection had impaired liver function." (PMID 23408990, 2013). "The most important of the possible studies is that of albumin versus plasma expanders in infections (non-SBP and SBP) as these questions have not been answered." (PMID 24222902, 2013). "The predictive model of mortality due to infection in dialysis patients demonstrated that non-response, DM, age, and low levels of albumin all predicted significantly higher mortality rates due to infection." (PMID 22935561, 2012).